ZNF138 (zinc finger protein 138)
Description:
May be involved in transcriptional regulation as a repressor.
Synonyms: pHZ-32
Tractability: PROTAC: ubiquitination databases record sites on it.
Gene: Protein-coding gene on chromosome 7 (64,794,388 to 64,833,681, forward strand). Ensembl gene ENSG00000197008.
Subcellular location: Nucleus
Pathways (Reactome):
Gene expression (Transcription): Generic Transcription Pathway
Gene Ontology:
Molecular function: protein binding; DNA-binding transcription factor activity, RNA polymerase II-specific; RNA polymerase II cis-regulatory region sequence-specific DNA binding
Biological process: regulation of DNA-templated transcription; regulation of transcription by RNA polymerase II
Cellular component: nucleus
Genetic constraint (gnomAD): Loss-of-function variants: 33 observed, 33.6 expected, observed/expected ratio (o/e) 0.98, 90% interval 0.74 to 1.31. The upper end of that interval is the gene's LOEUF score, 1.31, which puts it in group 5 of 6, group 1 being the genes least tolerant of losing a copy. Missense variants: 360 observed, 387.53 expected, observed/expected ratio (o/e) 0.93, 90% interval 0.85 to 1.01. Synonymous variants: 139 observed, 125.47 expected, observed/expected ratio (o/e) 1.11, 90% interval 0.96 to 1.27.
Homologues: Orthologues: chimpanzee ZNF727 (49% identical). Paralogues in human: ZNF85 (77% identical), ZNF681 (71% identical), ZNF708 (71% identical), ZNF724 (71% identical), ZNF93 (71% identical), ZNF254 (71% identical), ZNF429 (70% identical), ZNF43 (69% identical), ZNF486 (67% identical), ZNF728 (67% identical), ZNF726 (67% identical), ZNF493 (66% identical), and 164 more.
Diseases named in the same sentence as ZNF138 in open-access papers:
ZNF138 is named in the same sentence as 7 diseases in open-access papers, as found by Europe PMC text mining. Sharing a sentence is not in itself a finding about the gene and the disease. The quoted sentences say what the papers report.
cancer (3 papers, 2019 to 2023). A tumor composed of atypical neoplastic, often pleomorphic cells that invade other tissues. "The literature shows that some KZNFs are up-regulated in cancer, including ZNF695, ZNF320, ZNF200, ZNF354A, ZNF707, ZNF138 and so on." (PMID 37370088, 2023). "Interestingly, cancer‐related upregulation of ZNF695, ZNF714, and ZNF138 mirrors the differential expression observed between pluripotent stem cells and differentiated cells." (PMID 30444046, 2019).
tumor (1 paper, 2019). "Within these 148 comparisons, significantly higher expression in normal tissues compared to tumor tissues was observed only in six cases (ZNF138 in KIRC and THCA, ZNF200 in THCA, ZNF273 in PRAD, ZNF485 in THCA, and ZNF789 in KICH)." (PMID 30444046, 2019).
ZNF138 also shares sentences with these, for which no sentence is quoted: breast carcinoma (1 paper); metabolic syndrome (1); ovarian carcinoma (1); Temple syndrome (1); Williams syndrome (1).